SRPK1 (SRSF protein kinase 1)
Diseases named in the same sentence as SRPK1 in open-access papers (continued):
Sharing a sentence is not in itself a finding about the gene and the disease.
prostate carcinoma (20 papers, 2010 to 2025). A carcinoma that arises from epithelial cells of the prostate gland. "As reported, inhibition or knockdown of SRPK1 can remarkably prevent in vitro and in vivo angiogenesis and associated with tumor growth of Wilms’ tumor and prostate cancer, highlighting its potential as a novel drug target." (PMID 35192432, 2022). "In the present study, we aimed to investigate SRPK1 expression in prostate cancer (PCa) and its association with cancer progression." (PMID 26500332, 2016). "High MYC expression is associated with increased levels of SRPK1 in patient samples, and overexpression of MYC sensitizes prostate cancer cells to SRPK1 inhibition using pharmacological and genetic strategies." (PMID 38775167, 2024). "Pharmacological inhibition of SRPK1 in PC3 prostate cancer cells, reduces cell proliferation, invasion and migration." (PMID 35583632, 2022). "For example, SRPK1 was found to be aberrantly upregulated in colon adenocarcinoma, pancreatic cancer, prostate cancer, and hepatocellular carcinoma." (PMID 35192432, 2022). "SRPK1 silencing in prostate cancer cells was found to result in preferential splicing of the anti-angiogenic VEGFA isoform." (PMID 35583632, 2022). "We recently demonstrated that inhibition of the splice factor kinase SRPK1 with the compound SPHINX reduces prostate cancer xenograft growth through an anti-angiogenic alteration of VEGFA splicing." (PMID 33846420, 2021). "SRPK1 is a protein that is dysregulated also in other types of cancer, and this is why SRPK1 inhibition is considered a potential therapeutic target in prostate cancer." (PMID 31934531, 2019). "In prostate cancer, SRPK1 overexpression was noted in both cancer and its precursor, PIN (prostatic intraepithelial neoplasia), and was associated with a higher tumor stage." (PMID 31861708, 2019). "The SR protein kinase SRPK1 that modulates the activity of SR proteins is up-regulated in prostate cancer and has already given encouraging results as a potential therapeutic target in mouse models." (PMID 28382513, 2017). "Both the knockdown and pharmacological inhibition of SRPK1 shifts the ratio of splice isoforms in favour of the anti-angiogenic isoform of VEGFA165b, and we have proposed that targeting SRPK1 could be a viable avenue in prostate cancer." (PMID 36895328, 2023). "Indeed, WT1 repressed SRPK1 transcription in a non‐tumoral Denys Drash Syndrome podocyte cell line, whereas a more recent study reported that WT1 acts as a transcriptional activator of SRPK1 in prostate cancer and leukaemia cells." (PMID 34092037, 2021). "Our previous work on the splice factor kinase SRPK1 in the prostate cancer context demonstrated that its inhibition may set the scene for novel treatments." (PMID 33846420, 2021). "Meanwhile, SRPK1 in prostate cancer is shown to promote angiogenesis." (PMID 32106418, 2020). "In addition to SRPK1, another member of SRPKs, SRPK2, is suggested to promote the growth and metastasis of prostate cancer, although SRPK2 targets associated with these phenomena have not been identified." (PMID 32106418, 2020). "To summarize, targeting SRPK1 could treat prostate cancer by suppressing the VEGF-induced angiogenesis." (PMID 31861708, 2019). "Furthermore, SRPK1 regulates VEGF splicing and activity in prostate cancer: SRPK1 knockdown results in up-regulation of the anti-angiogenic isoform VEGFxxxb and decreased angiogenesis in a xenograft model." (PMID 31666932, 2019). "Both Kif3b and SRPK1 were expressed at significantly higher levels in areas where the prostate epithelium is invading into the surrounding stroma, further correlating their overexpression in the process of prostate cancer invasion and metastasis." (PMID 29904055, 2018). "Another splicing regulator that changes expression in prostate cancer is the protein kinase SRPK1." (PMID 28382513, 2017).
prostate carcinoma (continued). "For instance, LIMK2 downregulated NKX3.1 to increase the oncogenicity of castration-resistant prostate cancer, and overexpressed LIMK2 exhibited as a facilitator of triple-negative breast cancer metastasis by regulating SRPK1." (PMID 37189142, 2023). "SRPK1, a member of SRPK, is shown to be highly expressed in various cancers including breast and prostate cancers." (PMID 32106418, 2020). "In order to assess the efficacy of SRPK1 inhibition by SPHINX on substrate phosphorylation, we previously showed that the treatment of PC3 prostate cancer cells with SPHINX led to reduced levels of phosphorylated SR proteins coinciding with increased expression of anti-angiogenic VEGFA." (PMID 36895328, 2023). "This has been established through use of SRPK1 inhibiting compounds SRPN340 and Sphinx31 in a variety of tissues, including the kidney, retinal epithelium, peripheral neurones, prostate cancer, and acute myeloid leukaemia." (PMID 37456522, 2023). "Similarly, SRPK1 promotes NF-КB signalling in both breast and colorectal cancer and AS of the pro-angiogenic VEGF isoform in melanoma, NSCLC and prostate cancer." (PMID 35583632, 2022). "Upregulation of SRPK1 drives phosphorylation and nuclear translocation of the splicing factor SRSF1, which enhances splicing of the pro‐angiogenic VEGF165 isoform in Wilms Tumour, melanoma and prostate cancer." (PMID 34092037, 2021). "Quantitative analysis of an independent prostate cancer progression TMA cohort (University of Calgary) of 98 patients showed that both Kif3b and SRPK1 display significantly higher expression levels in prostate cancer epithelium compared to benign hyperplasia epithelium." (PMID 29904055, 2018). "SRPK1 inhibition keeps SRSF1 in the cytoplasm and, as a result, decreases the ability of the prostate cancer cell line PC-3 to form tumours in mouse xenografts, probably through changed patterns of VEGF mRNA splicing depriving prostate cancer cells from developing a blood supply." (PMID 28382513, 2017). "High SRPK1 expression and negative PTEN have a synergistic effect on adverse clinical outcomes in prostate cancer." (PMID 36869126, 2023).
glioma (15 papers, 2015 to 2026). A benign or malignant brain and spinal cord tumor that arises from glial cells (astrocytes, oligodendrocytes, ependymal cells). "Knocking down SRPK1 significantly reduced the proliferation, migration, and invasion abilities of the glioma cell lines U118MG and LN229." (PMID 38397980, 2024). "In conclusion, the expression of SRPK1 is positively correlated with the grade of gliomas and negatively correlated with patient prognosis, serving as an independent prognostic indicator." (PMID 38397980, 2024). "To clarify the expression of SRPK1 in various glioma cell lines, we selected 10 glioma cell lines and performed immunoblotting." (PMID 38397980, 2024). "To elucidate how SRPK1 affects the occurrence of glioma, we conducted RNA transcriptome sequencing of the normal cell group and the SRPK1-shRNA-LN229 cell group." (PMID 38397980, 2024). "SRPK1 regulates the proliferation, invasion, and migration of glioma cells through the Wnt/β-catenin/JAK-2/STAT-3 pathway." (PMID 38397980, 2024). "Similar results were obtained in other glioma cell lines, such as a significant decrease in proliferation ability in U343 cells after silencing SRPK1 and a significant inhibition of migration and invasion abilities." (PMID 38397980, 2024). "Knocking down SRPK1 leads to a significant decrease in the proliferation, migration, and invasion abilities of gliomas." (PMID 38397980, 2024). "SRPK1 promotes the proliferation, migration, and invasion of gliomas through the activation of the Wnt/β-catenin and JAK-2/STAT-3 signaling pathways." (PMID 38397980, 2024). "High-intensity immunohistochemistry results demonstrated that SRPK1 is positively associated with poor prognosis in grade III gliomas (HR = 2.01, 95% CI 1.47–2.30, p = 0.026) and grade IV gliomas (HR = 1.92, 95% CI 1.38–2.25, p = 0.017)." (PMID 38397980, 2024). "The high expression of SRPK1 promotes the malignant phenotype of glioma cells, while silencing SRPK1 induces cisplatin resistance and apoptosis in glioblastoma cells." (PMID 38397980, 2024). "SRPK1 promotes the proliferation, migration, and invasion of gliomas by activating the Wnt/β-catenin and JAK-2/STAT-3 signaling pathways." (PMID 38397980, 2024). "The expression of SRPK1 is positively correlated with the grade of glioma and negatively correlated with patient prognosis, serving as an independent indicator for glioma prognosis assessment." (PMID 38397980, 2024). "Under normoxic and moderately hypoxic conditions, knocking down SRPK1 inhibits the malignant progression of glioma cells, induces apoptosis in glioma cells, and suppresses AKT/E1F4E phosphorylation." (PMID 38397980, 2024). "For instance SRPK1 has been implicated in promoting AKT signalling in breast, colorectal, esophageal, endometrial and pancreatic cancer as well as glioma, HCC and T-ALL." (PMID 35583632, 2022). "Although it suppressed proliferation, migration, invasion, angiogenesis, and cell cycle progression, SRPK1 downregulation also suppressed apoptosis and at the same time induced resistance to chemotherapy in preclinical glioma studies." (PMID 31861708, 2019). "SRPK1 dissimilarly impacts the growth, metastasis, chemosensitivity and angiogenesis of glioma in hypoxic conditions." (PMID 28606154, 2017). "In uveal and blue-nevus melanomas, mutations in the SF3B1 splicing factor arise recurrently; in carcinomas and gliomas, the regulator SRPK1 is overexpressed." (PMID 28653984, 2017). "SRPK1 has been reported to be over-expressed in multiple cancers including prostate, breast, lung and glioma." (PMID 28977917, 2017). "In this study, we found that SRPK1 plays an important role in the development of gliomas." (PMID 38397980, 2024). "A stable shRNA-LN229 cell line was constructed, and using a nude mouse model, it was found that stable knockout of SRPK1 significantly reduced the tumorigenic ability of glioma cells, as evidenced by a significant decrease in the subcutaneous tumor volume and weight in nude mice." (PMID 38397980, 2024).
glioma (continued). "In this study, we have demonstrated that SRPK1 is a potential therapeutic target for gliomas." (PMID 38397980, 2024). "As a novel biomarker for gliomas, SRPK1 provides a potential target for the treatment of gliomas." (PMID 38397980, 2024). "Based on these findings, we speculate that the activation of the Wnt/β-catenin and JAK-2/STAT-3 signaling pathways by SRPK1 promotes the proliferation, migration, and invasion of gliomas." (PMID 38397980, 2024). "This study provides a novel molecular marker, SRPK1, for the diagnosis and treatment of gliomas." (PMID 38397980, 2024). "Silencing SRPK1-related signaling pathways may provide potential therapeutic options for glioma patients." (PMID 38397980, 2024). "We have demonstrated that SRPK1 is highly expressed in gliomas." (PMID 38397980, 2024). "SRPK1 significantly promotes the occurrence and development of gliomas." (PMID 38397980, 2024). "Furthermore, high expression of SRPK1 in glioma tissues often correlated with high expression of β-catenin and p-JAK2." (PMID 38397980, 2024). "SRPK1 is involved in the regulation of several mRNA processing pathways including alternative splicing, and overexpression of SRPK1 has been reported in multiple cancers including prostate, breast, lung, and glioma." (PMID 36186578, 2022). "Interestingly aberrant SRPK1 expression was consistently found in glioma tissue samples and cell lines, though its expression has scarcely been found in normal glial cells." (PMID 35583632, 2022). "SRPK1 has recently been suggested as a potential new molecular target that could be employed to facilitate the treatment of patients with early-stage gliomas, owing to its ability to regulate cell growth, metastasis, chemosensitivity and glioma angiogenesis." (PMID 36172261, 2022). "Similarly in glioma cells, hypoxic conditions were found to reduce the impact of SRPK1 inhibition on tumour growth, invasion and migration." (PMID 35583632, 2022). "Four studies examined the role of SRPK1 in glioma development." (PMID 35583632, 2022). "However, SRPK1 overexpression was linked with high proliferative activity (as measured with Ki67 IHC) and shorter survival in glioblastomas (WHO grade IV gliomas)." (PMID 31861708, 2019). "SRPK1 has been found upregulated in low-grade gliomas and related to patient prognosis." (PMID 26273588, 2015). "Moreover, SRPK1 knockdown inhibited glioma cells growth, invasion, and migration in normoxic condition." (PMID 26273588, 2015). "However, the specific mechanism by which SRPK1 regulates glioma cell proliferation remains unclear, and there is still an urgent need to continue exploring SRPK1-related signaling pathways in gliomas to find new therapeutic approaches." (PMID 38397980, 2024). "Moreover, the effects of SRPK1 knockdown on cell growth, migration and invasion in glioma could be reversed in hypoxia." (PMID 28606154, 2017). "Previous studies have shown that various oncogenes, such as SRPK1 and TMEM64, promote glioma proliferation, migration, and invasion by activating Wnt/β‐catenin signaling." (PMID 40589077, 2025). "Overexpression of SRPK1 activates the Wnt/β-catenin and JAK-2/STAT-3 signaling pathways, promoting the proliferation, migration, and invasion of gliomas." (PMID 38397980, 2024). "Activation of serine/arginine-rich splicing factor kinase 1 (SRPK1) expression which regulates phosphorylation of Akt and controls of VEGF splicing, induces the PI3K/Akt pathway and angiogenesis in glioma under normoxic conditions." (PMID 30583549, 2018). "Moreover, SRPK1 directly regulates the Wnt/β-catenin and JAK2/STAT-3 signaling pathways, thus promoting glioma development." (PMID 41141389, 2026). "Studies have reported that SRPK1 is aberrantly expressed in gliomas, while no significant abnormal expression is observed in normal glioma cells." (PMID 38397980, 2024). "SRPK1 (SRSF protein kinase 1) is highly expressed in gliomas but is not expressed in normal tissues." (PMID 38397980, 2024).
glioma (continued). "Research has found that SRPK1 is aberrantly expressed in both the tissue and cells of gliomas, while no abnormal expression has been observed in normal glioma cells." (PMID 38397980, 2024). "We observed high expression of SRPK1 in glioma tissues, while it is not expressed in normal tissues." (PMID 38397980, 2024). "Overexpression of SRPK1 activates the Wnt/β-catenin (wingless-int1/β-catenin) and JAK-2/STAT-3 (Janus kinase 2/signal transducer and activator of transcription 3) signaling pathways, promoting the proliferation, migration, and invasion of gliomas." (PMID 38397980, 2024). "For instance, while SRPK1 was highly expressed in gliomas, this was correlated with low rather than high-grade gliomas." (PMID 31861708, 2019). "SRPK1 and SRPK2 have been found overexpressed in different types of cancer including breast, colon, pancreatic carcinomas, leukemia, nonsmall cell lung carcinoma, squamous cell lung carcinoma, gliomas, ovary, and hepatocellular carcinoma." (PMID 26273588, 2015). "Notably, SRPK1 expression was most significant in WHO grade IV gliomas, while it was not expressed in normal brain tissue." (PMID 38397980, 2024). "Immunohistochemical analysis indicates that SRPK1 is expressed at low levels or not expressed in normal brain tissue, while it is highly expressed in grade IV gliomas and is expressed to a lesser extent in grade III gliomas, with expression levels positively correlated with glioma grading." (PMID 38397980, 2024).
lung carcinoma (12 papers, 2012 to 2025). "SRPK1 is associated with lung cancer progression by activating the transcriptional activity of the beta-catenin/T-cell factor (TCF) complex." (PMID 36304306, 2022). "Targeting SRPK1 with specific antibodies can lower its levels and reduce tumor spread and invasion in lung cancer." (PMID 39083441, 2025). "SRPK1 inhibition suppresses angiogenesis, metastasis, and the acquisition of a cancer stem cell phenotype, enhancing apoptosis in lung cancer and reducing the survival of cancer cells." (PMID 39083441, 2025). "In lung cancer, SRPK1 inhibition suppresses angiogenesis, metastasis, and the acquisition of a cancer stem cell phenotype." (PMID 36304306, 2022). "We recently showed that inhibition of SRPK1 enhances sensitivity of lung cancer cell lines to cisplatin." (PMID 23071587, 2012). "SRPK1 and its downstream targets have also been shown to be involved in tumour progression, with increased expression identified in different cancers, such as breast, prostate and lung cancers." (PMID 39095708, 2024). "SRPK1 is overexpressed and acts as an oncogene in multiple cancers, including lung cancer." (PMID 39095708, 2024). "However, a previous study shows that in lung carcinoma cells, cisplatin decreases both the transcript and protein levels of Tip60, resulting in nuclear translocation of SRPK1 and SRPK228." (PMID 32461560, 2020). "SRPK1 is upregulated in lung cancer and many other cancer types." (PMID 24278370, 2013). "Also of no great surprise is seeing SRPK1 when evaluating lung disease relevance since this gene is associated with lung cancer and RNA binding and protein kinase activity." (PMID 37250098, 2023).
acute myeloid leukemia (11 papers, 2018 to 2025). Acute myeloid leukemia (AML) is a group of neoplasms arising from precursor cells committed to the myeloid cell-line differentiation. "SPHINX inhibition of SRPK1 reduced the proliferation of and significantly increased rates of apoptosis in the acute myeloid leukaemia cell line Kasumi-1." (PMID 36895328, 2023). "Another recent study showed that SRPK1 maintains acute myeloid leukemia through effects on the isoform usage of epigenetic regulators including BRD451." (PMID 32859889, 2020). "Indeed, increased SRPK1 expression is observed in several tumour cell lines and found to be a genetic vulnerability in acute myeloid leukaemia; therefore, SRPK1 inhibition is suggested as an effective strategy to reduce tumour growth." (PMID 37607329, 2023). "In contrast, studies of SRPK1 in hematopoietic and lymphoid malignancies are rare and mostly focused on leukemias, such as acute adult T-cell leukemia, chronic myeloid leukemia, acute lymphoblastic leukemia, and acute myeloid leukemia." (PMID 36303126, 2022). "It has been found that SRPK1 was a genetic vulnerability of acute myeloid leukemia (AML) through effects on isoform usage of epigenetic regulators including BRD4." (PMID 35846993, 2022). "In AML (acute myeloid leukemia), SRPK1 low expression suppressed proliferation while it enhanced cell cycle arrest, apoptosis and survival." (PMID 31861708, 2019). "We recently identified the splicing kinase gene SRPK1 as a genetic vulnerability of acute myeloid leukemia (AML)." (PMID 30568163, 2018). "A CRISPR-Cas9 platform was used to screen for genetic vulnerabilities in acute myeloid leukaemia (AML) and identified SRPK1 as a potential therapeutic target." (PMID 36895328, 2023). "Interestingly, SRPK1 was also recently identified as a cell-essential gene in acute myeloid leukemia (AML) cell lines driven by oncogenes derived from MLL fusion genes such as MLL-AF9 and MLL-AF6." (PMID 31134126, 2019).